IFT88 (intraflagellar transport 88)
Diseases named in the same sentence as IFT88 in open-access papers (continued):
Sharing a sentence is not in itself a finding about the gene and the disease.
thyroid cancer (5 papers, 2019 to 2025). "The gene expression profile of IFT88-deficient thyroid cancer cells favors glycolysis and lipid biosynthesis." (PMID 40076734, 2025). "Here we established a mouse model with thyrocyte-specific loss of primary cilia (Tg-Cre;Ift88flox/flox) and human thyroid cancer cell lines with ciliary loss by silencing the KIF3A or IFT88 gene." (PMID 33602982, 2021). "Gene expression patterns in IFT88-deficient thyroid cancer cells favored glycolysis and lipid biosynthesis, which was beyond our understanding of the functions of IFT subunits and prompted us to re-examine the molecular mechanism of ciliopathies." (PMID 32010685, 2019). "A mouse model with PC loss mediated by intraflagellar transport 88 (IFT88) showed an irregularly dilated thyroid gland with destroyed follicles, malignant properties, and progressively differentiated thyroid cancer (PDTC), which reflected the pathogenicity of PC mutations in the thyroid gland." (PMID 38260150, 2023). "Thus, we analyzed the oligomeric status of VDAC1 in KIF3A-deficient or IFT88-deficient thyroid cancer cell lines." (PMID 33602982, 2021). "We found that KD of KIF3A or IFT88 in thyroid cancer cell lines led to increased apoptotic cell death." (PMID 33602982, 2021). "Defective ciliogenesis caused by deleting the IFT88 and KIF3A genes from thyroid cancer cell lines increased VDAC1 oligomerization following VDAC1 overexpression, thereby facilitating upregulation of mitochondria-dependent apoptosis." (PMID 33602982, 2021). "In contrast, the phenotype of IFT88 in thyroid cancer was more relevant to the mitochondrial oxidative function." (PMID 32010685, 2019). "In thyroid cancer cell lines, deletion or knockdown of IFT88 and KIF3A impaired ciliogenesis, enhanced VDAC1 oligomerization following VDAC1 overexpression, and disrupted mitochondrial morphology and function, ultimately promoting mitochondria-mediated apoptosis." (PMID 40389989, 2025). "In thyroid cancer cells, IFT88 has been implicated in metabolic reprogramming, but not in its tumor-suppressive capacity." (PMID 40076734, 2025). "However, the absence of IFT88/primary cilia does not augment the proliferation, migration, and invasion of thyroid cancer cells." (PMID 40076734, 2025).
glioblastoma (3 papers, 2023). The most malignant astrocytic tumor (WHO grade IV). "For instance, disruption of cilia formation in glioblastoma cell lines through knockdown of essential ciliogenesis genes, such as KIF3A or IFT88, had variable effects on tumor growth in vitro and in vivo." (PMID 38188300, 2023). "KLHDC8A mRNA expression correlated with the IFT88 and ARL13B expression in glioblastoma tissues." (PMID 36394953, 2023). "We first examined the relationship of ARL13B expression and another key ciliogenesis gene, IFT88, with the expression of other SHH pathway genes (SMO, GLI2, and SHH) in low-grade glioma (LGG) and high-grade glioblastoma (GBM) using TCGA datasets." (PMID 37830570, 2023).
liver cancer (3 papers, 2012 to 2020). An epithelial or non-epithelial malignant neoplasm that arises from the liver. "In conclusion, we demonstrated that blockage of primary cilia induced by IFT88 silencing positively promotes the malignant behaviors of liver cancer cells by activating autophagy." (PMID 31662980, 2019). "It seems that the role of IFT88 in HCC cell lines was the same as it in liver cancer stem cells." (PMID 31662980, 2019).
liver fibrosis (3 papers, 2024 to 2025). "Ift88-knockout (KO) mice are more susceptible to chronic carbon tetrachloride-induced liver fibrosis." (PMID 40076734, 2025). "Pathogenic variants in IFT88, which are related to Bardet-Biedl Syndrome, can lead to liver fibrosis, while ALMS1 (linked to Alström Syndrome) and NEK8 (associated with Nephronophthisis) are involved in renal cysts and liver fibrosis." (PMID 40277920, 2025). "Mutation of these three lysines to arginines can prevent ciliary loss and HSC activation during liver fibrosis, implying a potential for blocking IFT88 ubiquitination in the intervention of the fibrogenic process." (PMID 38351372, 2024). "This study shows that IFT88 is selectively downregulated during liver fibrosis, contributing to the specific loss of cilia on HSCs." (PMID 38351372, 2024). "Consistently, immunofluorescence microscopy analysis of α-SMA and vimentin, as well as Sirius red staining of liver sections, both demonstrated that loss of IFT88 in HSCs significantly enhanced CCl4-induced liver fibrosis." (PMID 38351372, 2024). "Ift88-knockout mice are more susceptible to chronic carbon tetrachloride-induced liver fibrosis." (PMID 38351372, 2024). "In the present study, we reveal a disruption of ciliary homeostasis during HSC activation and liver fibrosis, and uncover a significant decrease of a key ciliary factor, IFT88, upon profibrotic stimulation." (PMID 38351372, 2024). "In addition, we demonstrate that XIAP-mediated downregulation of IFT88 in HSCs exacerbates liver fibrosis." (PMID 38351372, 2024). "Importantly, ablating cilia by depleting IFT88 sensitizes mice to CCl4-induced liver fibrosis." (PMID 38351372, 2024). "Our data reveal the downregulation of IFT88 and the disruption of ciliary homeostasis during HSC activation and liver fibrosis." (PMID 38351372, 2024). "Blocking XIAP-mediated IFT88 degradation prevents TGF-β-induced HSC activation and liver fibrosis." (PMID 40076734, 2025). "Blocking XIAP-mediated IFT88 degradation ablates TGF-β-induced HSC activation and liver fibrosis." (PMID 38351372, 2024). "Moreover, we identify XIAP as an E3 ubiquitin ligase for IFT88 ubiquitination and proteasomal degradation, and establish a critical function for the XIAP–IFT88 axis in HSC activation and liver fibrosis." (PMID 38351372, 2024).
autosomal recessive polycystic kidney disease (2 papers, 2012 to 2023). An inherited disorder characterized by the development of cysts affecting the collecting ducts. "Defects in the Tg737 gene in mice are very similar to those seen in humans with autosomal recessive polycystic kidney disease, but so far no pathogenic IFT88 variants have been reported in PCD patients." (PMID 36901899, 2023). "Indeed, hypomorphic mutations in the mouse ift88 (previously called Tg737) gene, which encodes a ciliogenic IFT protein, result in malformation of primary cilia, and in the collecting ducts of kidney tubules this is accompanied by development of autosomal recessive polycystic kidney disease (PKD)." (PMID 22708495, 2012).
Bardet-Biedl syndrome (2 papers, 2008 to 2009). A ciliopathy with multisystem involvement. "The resemblance of both cep70 and cep131 morphants to those of zebrafish IFT57 and IFT88 makes the two proteins candidates for genes mutated in inherited human diseases similar to Bardet-Biedl syndrome in which cilia in a number of tissues are affected." (PMID 19254375, 2009).
basal cell carcinoma (2 papers, 2016 to 2023). A carcinoma involving the basal cells. "Conditional deletion of KIF3A or IFT88 in basal cell carcinoma leads to ciliary elimination and strong inhibition of tumorigenesis induced by mutant SMO." (PMID 27793025, 2016). "IFT88 is an intraflagellar transport protein and ARL13B is a regulatory GTPase; both are required for ciliogenesis and activation of canonical hedgehog signaling pathway in basal cell carcinoma and medulloblastoma." (PMID 36394953, 2023).
emphysema (2 papers, 2019 to 2021). "DiffCoEx analysis showed that four hub genes (IFT88, CCDC103, MMP10 and Bik) were consistently expressed in emphysema patients; these hub genes were enriched, respectively, for functions of cilium assembly and movement, proteolysis and apoptotic mitochondrial changes." (PMID 31419013, 2019).
medulloblastoma (2 papers, 2016 to 2023). A malignant, invasive embryonal neoplasm arising from the cerebellum. "ZNF423-depleted DAOY medulloblastoma cells are reproducibly deficient in translocation into the cilium of both Smoothened and IFT88, which are required for normal signal processing and specifically for expansion of GCPs." (PMID 27727273, 2016).
mitral valve prolapse (2 papers, 2022 to 2024). A fairly common and often benign valvular heart disorder characterized by redundancy or hooding of mitral valve leaflets so that they prolapse into the left atrium, often causing mitral regurgitation. "Intraflagellar Transport 88 knockout results in reduced primary cilia, and knockout from cardiac endothelium produces myxomatous degeneration similar to mitral valve prolapse seen in adult humans." (PMID 35326411, 2022). "Mice with Ift88 knockout in valvular cells show myxomatous degeneration of the mitral valve similar to that observed in adult humans with mitral valve prolapse." (PMID 35326411, 2022). "During the valve development, premature loss of primary cilia due to a missense mutation of a ciliary gene DZIP1 or by IFT88 conditional knockout in the valve interstitial cells induces an enhanced ECM synthesis, resulting in dysmorphic leaflets and, eventually, in mitral valve prolapse in adult." (PMID 38816374, 2024).
osteoarthritis (2 papers, 2020 to 2025). A noninflammatory degenerative joint disease occurring chiefly in older persons, characterized by degeneration of the articular cartilage, hypertrophy of bone at the margins and changes in the synovial membrane. "The IFT88 protein plays a crucial role in regulating cartilage thickness and the development of osteoarthritis in mice, functioning as a positive regulator of cartilage thickness." (PMID 40076734, 2025). "In mouse models of osteoarthritis, IFT88 preserves the Hh signaling threshold during physiological loading to regulate cartilage calcification, thereby protecting articular cartilage." (PMID 40076734, 2025).
acute kidney injury (1 paper, 2024). Sudden and sustained deterioration of the kidney function characterized by decreased glomerular filtration rate, increased serum creatinine or oliguria. "Furthermore, the reduced intraflagellar transport protein 88 (IFT88) expression in cisplatin-induced acute kidney injury (AKI) shortens primary cilia and leads to mitochondrial dysfunction." (PMID 39115943, 2024).
Anxiety (1 paper, 2023). Intense feelings of nervousness, tension, or panic often arise in response to interpersonal stresses. "Although the total distance and the distance traveled in the peripheral zone were significantly lower in the IFT88-KO mice than the control mice, this does not indicate an altered anxiety-related behavior; rather, it reflects a slower response to the new environment." (PMID 36322337, 2023).
bladder cancer (1 paper, 2023). "Our results revealed that PC loss caused by IFT88 silencing could promote SHH signalling pathways activated in bladder cancer cells and uncontrolled cell proliferation." (PMID 37101292, 2023).
bronchiectasis (1 paper, 2022). Segmental, irreversible dilation of the bronchial tree resulting in the accumulation of secretions which leads to obstruction. "Mice that have lost the IFT88 gene rapidly lose cilia and have been reported to develop bronchiectasis." (PMID 36505420, 2022). "Our finding of minimal differences in lung airway area and lung airway diameter comparing IFT88 KO mice to IFT88 control mice suggests that the development of a proinflammatory lung phenotype in IFT88 KO mice contributes to Mabs lung persistence independent of bronchiectasis." (PMID 36505420, 2022).
cervical cancer (1 paper, 2024). A primary or metastatic malignant neoplasm involving the cervix. "In conclusion, while further studies are needed to define the mechanisms underlying AATF action, our results provide novel evidence of the effect of AATF on ciliogenesis and VBL resistance through the regulation of NPHP3 and IFT88 expression in HeLa cervical cancer cells." (PMID 39408701, 2024).
depression (1 paper, 2025). "Like AC3 KO depression model mice, inducible IFT88 KO mice were found to have altered sleep patterns, which is a common phenotype in human depression patients." (PMID 39747370, 2025).
diabetes (1 paper, 2022). "Differential expression of proteins linked to cancer metastasis, such as the upregulation of vinculin and endoplasmin and downregulation of WWC3 and IFT88, was seen in the patients with diabetes." (PMID 35454982, 2022). "In addition, protein changes associated with cancer metastasis, such as the upregulation of vinculin and endoplasmin, and downregulation of WWC3 and IFT88, were seen in the patients with diabetes." (PMID 35454982, 2022).
glioma (1 paper, 2023). A benign or malignant brain and spinal cord tumor that arises from glial cells (astrocytes, oligodendrocytes, ependymal cells). "While there is a direct correlation between ARL13b expression and IFT88 expression in the TCGA for glioma, the nature of this relationship is unclear." (PMID 37830570, 2023). "Glioma cells overexpressing ARL13B also display reduced ciliary intraflagellar transport 88 (IFT88), suggesting that altered retrograde transport could further promote SMO/GLI accumulation." (PMID 37830570, 2023). "Future analyses of patient gliomas should determine whether IFT88 expression is proportionate to the number of ARL13B+ cilia in a tumor or dependent on the quantity of ARL13B within each cilium." (PMID 37830570, 2023).
Granuloma (1 paper, 2022). A compact, organized collection of mature mononuclear phagocytes, which may be but is not necessarily accompanied by accessory features such as necrosis. "It is noteworthy that histopathologic assessment showed a significant increase in granulomas and lung histiocytes at D54 in IFT88 KO mice compared to control mice with Mabs persisting in the lungs at this time point." (PMID 36505420, 2022).
infertile (1 paper, 2025). "IFT88 is a crucial component of the IFT-B subcomplex, male Ift88−/− mice is infertile." (PMID 41466333, 2025).
insulinoma (1 paper, 2019). "In βICKO islets and insulinoma cells depleted of Ift88, we found that EphA receptors were hyperphosphorylated and that this elevation in pEphA levels blocked insulin secretion from induced βICKO islets." (PMID 31831727, 2019). "To better understand the molecular underpinnings of EphA2/A3 upregulation, we next tested if depletion of Ift88 mRNA resulted in similar EphA3 upregulation in an insulinoma cell line, Min6m921." (PMID 31831727, 2019).
Kidney Cyst (1 paper, 2015). Abnormal fluid filled sac within the kidney, either acquired or congenital. "Unlike human ARPKD, which typically results in severe kidney phenotype, Ift88−/− mouse revealed only mild focal kidney cysts." (PMID 25999403, 2015).
male infertility (1 paper, 2025). The inability of the male to effect fertilization of an ovum after a specified period of unprotected intercourse. "Together, our findings establish CFAP57 as an important mediator of sperm flagellogenesis that orchestrates MYH10 and IFT88 positioning and intraflagellar transport dynamics to maintain flagellar integrity, providing molecular insights into MMAF-associated male infertility." (PMID 41466333, 2025). "IFT88, a key component of the IFT-B complex, plays a crucial role in the assembly of mouse sperm flagella, as its absence leads to defects in flagellar structure and male infertility In this study, Our IF and IEM analysis confirmed MYH10 pan-axonemal localization in sperm tail." (PMID 41466333, 2025).
McKusick-Kaufman syndrome (1 paper, 2025). McKusick-Kaufman syndrome is a very rare, genetic developmental disorder presenting in the neonatal period characterized by genitourinary malformations, polydactyly, and more rarely, congenital heart disease or gastrointestinal malformations. "In mutants for the ciliary genes Bbs8, Ift88 or McKusick-Kaufman syndrome (Mkks) gene, the expression domain of Gαi is expanded, such that it covers the entire lateral half of the HC." (PMID 40802839, 2025).
megalencephaly (1 paper, 2021). A congenital abnormality in which the occipitofrontal circumference is greater than two standard deviations above the mean for a given age. "Interestingly, mutations in some centrosomal/ciliary genes (e.g., Cep83, IFT88) can also lead to megalencephaly, i.e., larger brains." (PMID 34744618, 2021).
melanoma (1 paper, 2024). A malignant, usually aggressive tumor composed of atypical, neoplastic melanocytes. "A further ≈20% decrease in cancer cell viability was observed in PC-deficient IFT88−/− A375 human melanoma cells compared to the WT control under SD conditions in the absence of FBS." (PMID 39408701, 2024).
melasma (1 paper, 2023). "Our findings revealed decreased levels of NRF2, heme oxygenase-1, IFT88, and GLIs in lesional skin from melasma patients." (PMID 38001823, 2023). "We compared the expression levels of the nuclear factor E2-related factor 2 (NRF2), intraflagellar transport 88 (IFT88), and glioma-associated oncogene homologs (GLIs) in skin samples from patients with melasma, both in affected and unaffected areas." (PMID 38001823, 2023).
metastatic cancer (1 paper, 2024). A carcinoma which has spread from the original site of growth to another anatomic site. "We have demonstrated here, for the first time, an additional role for osteocyte primary cilia and the associated IFT88 pathway, in controlling TNF‐α secretion and altering metastatic cancer cell behavior." (PMID 37967351, 2024).
morbid obesity (1 paper, 2016). An excess of body weight, normally defined as an individual with a body mass index greater than 35 or a body weight greater than one hundred percent of ideal body weight. "Bbs1;CreLRb mice developed morbid obesity as a result of hyperphagia and reduced energy expenditure, in contrast to Ift88;CreLRb mice, which showed mild weight gain that was not a result of hyperphagia." (PMID 27482817, 2016).
oral-facial-digital syndrome 1 (1 paper, 2023). "IFT88 overexpression led to upregulation of IFT80/81, two critical components of IFTB complex, and caused downregulation of OFD1 (oral-facial-digital syndrome 1), a ciliogenesis suppressor." (PMID 37485393, 2023).
orofaciodigital syndrome I (1 paper, 2021). "In human ciliated cells, IFT88 (OMIM: 600,595) co-localizes with OFD1 (OMIM: 300,170), and genetic alterations in OFD1 cause Orofaciodigital Syndrome-1." (PMID 35145545, 2021).
ovarian carcinoma (1 paper, 2012). A malignant neoplasm originating from the surface ovarian epithelium. "Initially, we investigated the expression and localization of two IFT proteins, IFT20 and IFT88, essential for the assembly of primary cilia and found no obvious difference between normal human OSE cells and the two ovarian cancer cell lines." (PMID 23351307, 2012).
pulmonary fibrosis (1 paper, 2020). Chronic progressive interstitial lung disorder characterized by the replacement of the lung tissue by connective tissue, leading to progressive dyspnea, respiratory failure, or right heart failure. "Our data demonstrate that loss of endothelial Ift88 leads to EndMT and increased proliferation in vitro, and exacerbates bleomycin-induced pulmonary fibrosis in vivo." (PMID 32161282, 2020). "EndMT is also suggested to underlie heart and lung fibrosis, however, the mechanism linking endothelial Ift88, its effect on EndMT and organ fibrosis remains mainly unexplored." (PMID 32161282, 2020).
short rib-polydactyly syndrome (1 paper, 2025). Short rib-polydactyly syndromes are a group of bone malformations characterized by a narrow thorax and polydactyly (usually preaxial). "IFT52 is a core protein of IFT‐B1b that interacts with IFT88, which plays a vital role in cilium assembly, and its mutation can induce cilium disruption and result in short rib polydactyly syndrome." (PMID 39915276, 2025).
silicosis (1 paper, 2020). Silicosis is a respiratory disease caused by breathing in (inhaling) silica dust. "The levels of KIF3A and IFT88 were increased in rats exposed to silica for 4 weeks and decreased in the 24-week silicosis group compared with their control groups." (PMID 32042332, 2020).